METTL3 (methyltransferase 3, N6-adenosine-methyltransferase complex catalytic subunit)
Diseases named in the same sentence as METTL3 in open-access papers (continued):
Sharing a sentence is not in itself a finding about the gene and the disease.
Hyperglycemia (9 papers, 2022 to 2025). An increased concentration of glucose in the blood. "Under inflammation and oxidative stress conditions, METTL3 level decreased in islet cells, and islet β-cell deficiency of Mettl3 further induces hyperglycemia." (PMID 37484964, 2023). "Deficiency of WTAP was associated with a reduction of METTL3 levels and resulted in severe hyperglycemia and β-cell failure." (PMID 37484960, 2023). "METTL3-driven m6A modification in β-cells enhances insulin secretion, counteracting hyperglycemia and β-cell failure." (PMID 41194259, 2025). "In the β-cells of both T2D patients and a diabetic mouse model, decreased expression of METTL3/14 impairs the maturation of β-cells by decreasing the stability of MarfA mRNA, which leads to hyperglycemia and hypoinsulinemia." (PMID 38560499, 2024). "Mice with deletion of Mettl3/14 in Ngn3+ endocrine progenitor cells developed hyperglycemia and hypoinsulinemia 2 weeks after birth." (PMID 37484960, 2023). "Furthermore, mice with Mettl3/Mettl14 deletion in Ngn3+ endocrine progenitors developed hyperglycemia and hypoinsulinemia within 2 weeks after birth." (PMID 41585810, 2025). "In addition, mice with specific knockout of METTL3/14 in Ngn3+ endocrine progenitors develop hyperglycemia and hypoinsulinemia." (PMID 38560499, 2024). "The β-cell-specific deletion of METTL3 also induced cell failure and hyperglycemia." (PMID 36157472, 2022). "Meanwhile, in Pdx1+ pancreatic progenitor cells, absence of METTL3 could inhibit Hdac1 expression and further activate wnt/β-catenin and Notch/Hes1 pathways, leading to hyperglycemia and hypoinsulinemia, along with an atrophic pancreas, reduced islet mass, and abnormal increase in ductal formation." (PMID 39296713, 2024).
ocular melanoma (9 papers, 2019 to 2025). A melanoma that arises from the structures of the eye or ocular adnexa. "In some cancers, intracellular m6A hypomethylation in tumor cells due to decreased METTL3 expression was also found, which in turn induced recurrence of ocular melanoma and endometrial tumors." (PMID 37344779, 2023). "For instance, METTL3, an m6A ‘writer’, was downregulated in ocular melanoma tissues, and m6A demethylation of FOXM1 mRNA mediated by ALKBH5 was associated with uveal melanoma (UM) progression." (PMID 36264762, 2022). "A previous study reported that the expression of METTL3 was comparatively reduced in ocular melanoma tissues." (PMID 36264762, 2022). "m6A modification was decreased in ocular melanoma due to METTL3 downregulation and ALKBH5 upregulation, which promoted YTHDF1-mediated translation of histidine triad nucleotide-binding protein 2 (HINT-2), a tumor suppressor of ocular melanoma." (PMID 35164788, 2022). "To evaluate whether the global m6A level is related to tumorigenesis in ocular melanoma, we first inhibited the expression of methyltransferase METTL3 in normal pigmented cells and ocular melanoma cells." (PMID 31722709, 2019). "Thus, the decreased m6A level in ocular melanoma cells is likely due to the downregulation of METTL3 and upregulation of ALKBH5." (PMID 31722709, 2019). "Notably, one of the methylated transferases, METTL3, plays a dominant role in ocular melanoma." (PMID 36264762, 2022). "Similarly, we silenced the expression of methyltransferase METTL3 in ocular melanoma." (PMID 31722709, 2019). "In addition to YTHDF1 and METTL3, which affect ocular melanoma by influencing their downstream target genes, FTO has also been found to play a key role in ocular melanoma." (PMID 41315216, 2025). "Accordingly, decreased METTL3 and upregulated ALKBH5 were observed in ocular melanoma cells." (PMID 31722709, 2019). "Notably, the expression of the known m6A “writer” METTL3 was also decreased in ocular melanoma tissue compared to normal melanocyte tissue (p < 0.05), while the opposite trend was observed for m6A “eraser” ALKBH5 (p < 0.01)." (PMID 31722709, 2019).
pulmonary fibrosis (9 papers, 2022 to 2025). Chronic progressive interstitial lung disorder characterized by the replacement of the lung tissue by connective tissue, leading to progressive dyspnea, respiratory failure, or right heart failure. "In pulmonary fibrosis, METTL3 drives fibroblast activation and ECM deposition via selective m6A programs, with the KCNH6-YTHDF1 axis linked to myofibroblast transition." (PMID 41515964, 2025). "Collectively, these findings demonstrate that METTL3 promotes pathological lung remodeling through multiple m6A-dependent mechanisms and represents a promising epigenetic therapeutic target in pulmonary fibrosis." (PMID 41515964, 2025). "Clinical Implications (Pulmonary fibrosis): METTL3-targeted inhibition, coupled with established anti-fibrotic therapies, should be tested in rigorously staged preclinical models." (PMID 41515964, 2025). "While METTL3’s role in pulmonary fibrosis has been increasingly elucidated, research on its function in other types of interstitial lung diseases (ILDs) remains limited." (PMID 41515964, 2025). "Collectively, these findings position METTL3 as a key epigenetic modulator in PM2.5-induced pulmonary fibrosis." (PMID 41515964, 2025). "As a methyltransferase, METTL3‐mediated m6A modification is widely involved in lung injury, inflammation, and pulmonary fibrosis." (PMID 38757482, 2024). "Moreover, in radiation-induced lung injury (RILI), METTL3 facilitates YY1 mRNA methylation, and its stability is enhanced by IGF2BP1, leading to fibroblast activation and pulmonary fibrosis, underscoring its critical role in radiation-associated lung damage." (PMID 41515964, 2025). "In diseases such as ALI/ARDS, pulmonary fibrosis, and lung infections, where effective therapeutic options remain limited, targeting METTL3 and the m6A pathway may offer novel treatment avenues." (PMID 41515964, 2025). "METTL3 has emerged as a key regulator of pulmonary-fibrosis pathogenesis." (PMID 41515964, 2025). "Pulmonary fibrosis: Targeting METTL3-dependent myofibroblast programs (e.g., KCNH6–YTHDF1) may synergize with approved anti-fibrotics; staged designs can separate injury and remodeling phases." (PMID 41515964, 2025). "Similarly, the m6A methylation regulator methyltransferase-like 3 (METTL3) can be considered as an important biomarker for diagnosing pulmonary fibrosis occurrence because of its low expression in pulmonary fibrosis." (PMID 36494831, 2022). "Whereas METTL3 has been reported to enhance the translation of the transcription factor Nrf, which can alleviate PM2.5-induced pulmonary fibrosis." (PMID 39756462, 2025). "METTL3 promotes the YTHDF1-dependent translation of KCNH6, thereby accelerating EMT and myofibroblast proliferation, worsening idiopathic pulmonary fibrosis (IPF)." (PMID 41515964, 2025). "Regarding pulmonary pathophysiology, METTL3-mediated m6A is tied to disease initiation and progression in conditions such as asthma, chronic obstructive pulmonary disease (COPD), idiopathic pulmonary fibrosis (IPF), lung infections, acute respiratory distress syndrome (ARDS)." (PMID 41515964, 2025). "Regarding m6A writers, the methyltransferases METTL3, METTL14, and ZC3H13 have been identified as potential biomarkers for early diagnosis of pulmonary fibrosis and as prognostic indicators for patients with pulmonary fibrosis." (PMID 39756462, 2025). "In airway and alveolar epithelium, METTL3 targets SOCS3/STAT3, ACSL4, KCNH6, PTEN and others to promote epithelial–mesenchymal transition, ferroptosis and barrier disruption, thereby tightly coupling inflammatory signaling to structural remodeling in COPD, pulmonary fibrosis and ALI/ARDS." (PMID 41515964, 2025). "In bleomycin‐treated mice, upregulated METTL3 has been identified to enhance the m6A modification of KCNH6 mRNA in a YTHDF1‐dependent manner to promote its translation and expression, which evokes the phenotypic conversion of alveolar myofibroblasts and pulmonary fibrosis." (PMID 37537731, 2023).
retinoblastoma (9 papers, 2020 to 2023). A malignant tumor that originates in the nuclear layer of the retina. "Specifically, METTL3 was found upregulated in retinoblastoma, and its silence decreased retinoblastoma malignancy by regulating PI3K/Akt signaling, probably by affecting two downstream effectors P70S6K and 4EBP1." (PMID 36977668, 2023). "In retinoblastoma cell lines, METTL3 was higher than that in normal ARPE-19 cells, and upregulation of METTL3 promoted the growth of retinoblastoma via the PI3K/AKT/mTOR signaling pathway." (PMID 36830067, 2023). "In retinoblastoma, the m6A methyltransferase METTL3 promotes retinoblastoma progression through the PI3K/AKT/mTOR pathway." (PMID 35945641, 2022). "Furthermore, METTL3 promotes the proliferation of retinoblastoma cells by activating PI3K–Akt–mTOR signaling pathways." (PMID 37858219, 2023). "METTL3 has been shown to elevate the mRNA levels of P70S6K and 4EBP1 to promote retinoblastoma (RB) progression." (PMID 34315512, 2021).
systemic lupus erythematosus (9 papers, 2020 to 2026). An autoimmune multi-organ disease typically associated with vasculopathy and autoantibody production. "METTL3 and m6A levels in B cells from systemic lupus erythematosus (SLE) patients and lupus-prone mice were analyzed using m6A dot blot, RT-qPCR, western blotting, and flow cytometry." (PMID 40506739, 2025). "The reciprocal regulation between METTL3 and PAX5 highlights a critical mechanism underlying B-cell activation and persistence in autoimmune conditions like lupus." (PMID 40506739, 2025). "Consistently, we identified that elevated METTL3 contributes to B-cell hyperresponsiveness in lupus, suggesting a shared role of METTL3 in B-cell autoimmunity." (PMID 40506739, 2025). "In summary, our study identifies elevated levels of METTL3 in the B cells of lupus mice and patients, with a positive correlation to disease activity in SLE patients." (PMID 40506739, 2025). "In summary, we uncovered an essential role of METTL3 in regulating T-cell activation, effector T-cell differentiation, and the lupus phenotype in SLE." (PMID 37013484, 2023). "Pharmacological inhibition of METTL3 in our cGVHD model significantly aggravated the lupus-like phenotype, as indicated by higher levels of autoantibodies in the serum, more severe kidney damage, and more accumulation of immune complexes in the glomerulus." (PMID 37013484, 2023). "To assess the role of METTL3 in the pathogenesis of lupus, we generated a cGVHD mouse model by tail vein injection of lymphocytes from DBA2 mice into B6D2F1 mice, followed by intraperitoneal administration of STM2457 or DMSO control." (PMID 37013484, 2023). "Additionally, METTL3 expression was elevated in B cells from the spleen, lymph nodes, and bone marrow of lupus mice." (PMID 40506739, 2025). "Given the established importance of METTL3 in B-cell immunity, we explored its potential involvement in lupus B cells using a pristane-induced lupus mouse model." (PMID 40506739, 2025). "Moreover, METTL3 inhibition increased antibody production and aggravated the lupus-like phenotype in cGVHD mice." (PMID 37013484, 2023). "In summary, these data support that catalytic inhibition of METTL3 contributes to autoantibody production and the lupus-like phenotype in cGVHD mice, potentially by promoting CD4+ T cell activation and affecting the imbalanced differentiation of effector T cells." (PMID 37013484, 2023). "Additionally, pharmacological inhibition of METTL3 enhanced autoantibody production and exacerbated the lupus-like phenotype in cGVHD mice." (PMID 37013484, 2023). "In our study, we observed significantly elevated METTL3 expression in B cells from both SLE patients and lupus mice." (PMID 40506739, 2025). "Western blot analysis showed elevated expression of the methyltransferases METTL3 and METTL14, and reduced expression of the demethylase ALKBH5 in lupus mice." (PMID 40506739, 2025). "We observed that pharmacological inhibition of METTL3 by STM2457 promoted CD4+ T-cell activation and reduced the population of Treg cells in a humoral SRBC model and lupus-like cGVHD model." (PMID 37013484, 2023). "The first available data were focused on the mRNA expression of m6A writers (METTL3, METTL14, and WTAP), erasers (FTO and ALKBH5) and readers (YTHDF2) in peripheral blood mononuclear cells (PBMCs) from lupus affected patients." (PMID 33807762, 2021).
colon adenocarcinoma (8 papers, 2020 to 2026). "The mutation in METTL3 is in the region of MT-A70 and the diseases associated with the mutation in METLL3 include colon adenocarcinoma, rectal adenocarcinoma, and rectum adenocarcinoma." (PMID 40177651, 2025). "Based on TCGA pan-cancer correlation analysis, it was demonstrated that ZNRD1-AS1 expression was significantly and positively correlated with METTL3 in all tumor types, with the exception of colon adenocarcinoma, and with METTL14 in all cancer types (R > 0.3), including LUAD and LUSC." (PMID 36581942, 2022). "Notably, overexpression of METTL3 was observed in 10 out of 31 cancer types, including colon adenocarcinoma (COAD) and rectum adenocarcinoma (READ)." (PMID 33411363, 2021). "The results showed that METTL3 was highly expressed in 17 tumors including bladder urothelial carcinoma (BLCA), extrahepatic cholangiocarcinoma (CHOL) and colon adenocarcinoma (COAD)." (PMID 32626532, 2020).
depression (8 papers, 2021 to 2025). "Another methyltransferase, METTL3, was also associated with depression." (PMID 37175269, 2023). "Considering that METTL3, METTL14, and WTAP are core components of the methyltransferase complex, and FTO and ALKBH5 are major demethylases, it was reported that METTL3, FTO, and ALKBH5 were implicated in the pathology of depression." (PMID 37175269, 2023). "Consistently, depletion of METTL3 in mice also showed reduced hippocampal neurogenesis, decreased spatial memory, and depression-like behavior." (PMID 37189411, 2023). "Another bioinformatic analysis study found that in depression rat models, genes such as Mettl3, Fto, Ythdf2, and Hnrnpc are significantly upregulated, with 66.7% of these genes being core genes regulated by m6A modification, highlighting their crucial role in the onset and progression of depression." (PMID 40590504, 2025). "Next, we performed differential gene analysis of m6A regulators in depression and found that FTO, RBM15B, METTL3, LRPPRC, HNRNPC, ZC3H13, and YTHDF2 were significantly upregulated in depressed rats." (PMID 35480327, 2022). "In one study, global m6A methylation is decreased in the whole blood of both human and mice after acute stress, and in another study, ALKBH5 and FTO as m6A demethylases and METTL3, METTL14, and WTAP as m6A methyltransferases are altered in the MDD patients and the depression models." (PMID 38773146, 2024). "The present study suggested that the m6A-modifying enzyme METTL3, as well as WTAP, may play a key role in the pathogenesis and treatment of depression, which provided some hints for the development of new antidepressant drugs at the epitranscriptomic level." (PMID 37175269, 2023). "In conclusion, our study found that hypericin improved depression-like behaviors in UCMS mice, while upregulating METTL3 and WTAP expression in the hippocampi of UCMS mice and modifying the neurotrophin signaling pathway through m6A modification to exhibit antidepressant effects." (PMID 37175269, 2023). "This suggests that METTL3 and WTAP-mediated changes in m6A modifications may be a potential mechanism for the pathogenesis of depression and the efficacy of antidepressants, and that the neurotrophin signaling pathway plays a key role in this process." (PMID 37175269, 2023). "RNA methyltransferases (METTL3, METTL14, and WTAP) and demethylases (FTO and ALKBH5) are altered in the MDD patients and the mouse models of depression." (PMID 38773146, 2024).
diabetic retinopathy (8 papers, 2020 to 2025). "Similarly, in diabetic retinopathy, METTL3 deficiency exacerbates RPE apoptosis under hyperglycemic conditions, an effect that can be alleviated through miR-25-3p/PTEN/Akt signaling." (PMID 40547022, 2025). "We aimed to explore the regulatory effects of methyltransferase-like 3 (METTL3) on diabetic retinopathy (DR) by regulating the m6A modification of SOX2 mRNA and elucidating the underlying molecular mechanism." (PMID 40727611, 2025). "However, it is still unclear whether METTL3 involves in the pathogenesis of diabetic retinopathy (DR)." (PMID 32365051, 2020). "A previous study revealed that m6A transferase METTL3 installed the m6A modification and enhanced the stability of SNHG7 in diabetic retinopathy." (PMID 39195675, 2024).
intrahepatic cholangiocarcinoma (8 papers, 2022 to 2026). A carcinoma that arises from the intrahepatic bile duct epithelium in any site of the intrahepatic biliary tree. "The overexpression of METTL3 in intrahepatic cholangiocarcinoma (ICC) patients is associated with poor prognosis." (PMID 40823087, 2025). "have demonstrated that METTL3 promoted apoptosis, autophagy, and pyroptosis of glutamic acid-induced intrahepatic cholangiocarcinoma (ICC) by interacting with DGCR8 and modulating the miR-30b-5p/PIK3R2 axis in an m6A-dependent manner." (PMID 37182154, 2023). "Our aim was to explore the biological function and clinical significance of the m6A methyltransferase METTL3 in intrahepatic cholangiocarcinoma (ICC)." (PMID 35094011, 2022). "Moreover, in intrahepatic cholangiocarcinoma, inhibiting METTL3 by STM2457 may be an effective approach to arresting malignant tumor growth and overcoming chemotherapy resistance." (PMID 39132158, 2024). "The METTL3 inhibitor STM2457 suppresses growth, invasiveness, and migration of intrahepatic cholangiocarcinoma (ICC) cells, induces apoptosis, and triggers cell cycle arrest, thereby significantly suppressing ICC progression and exhibiting superior anti-tumor effects (Ref." (PMID 40488318, 2025).
pulmonary hypertension (8 papers, 2021 to 2025). Increased pressure within the pulmonary circulation due to lung or heart disorder. "Although METTL3 has been extensively studied in cancer biology and stem cell differentiation, its role in pulmonary hypertension (PH) and pulmonary arterial hypertension (PAH) has recently gained attention." (PMID 41515964, 2025). "To elucidate the role of METTL3 in the progression of pulmonary hypertension, we generated endothelial-specific Mettl3 knockout mice." (PMID 38741032, 2024). "Moreover, the METTL3/YTHDF2/PTEN axis was proven to promote hypoxia-induced pulmonary artery hypertension." (PMID 36911406, 2023). "In a rat model of hypoxia-inducted pulmonary arterial hypertension and in hypoxia-induced or PDGF-BB-induced PASMCs, both METTL3 and YTHDF1 are upregulated." (PMID 39155349, 2024). "Down-regulation of m6A modification by knockdown of METTL3 and METTL14 can delay the progression of pulmonary hypertension by inhibiting the proliferation and migration of pulmonary arterial smooth muscle cells (Zhou X.-L." (PMID 35836571, 2022).